TGM7 (transglutaminase 7)
Description:
Catalyzes the cross-linking of proteins and the conjugation of polyamines to proteins.
Synonyms: TGMZ
Tractability: No criterion of Open Targets' tractability assessment is met for any kind of drug.
Gene: Protein-coding gene on chromosome 15 (43,276,271 to 43,302,255, reverse strand). Ensembl gene ENSG00000159495.
Gene Ontology:
Molecular function: protein binding; protein-glutamine gamma-glutamyltransferase activity
Biological process: peptide cross-linking
Genetic constraint (gnomAD): Loss-of-function variants: 71 observed, 80.5 expected, observed/expected ratio (o/e) 0.88, 90% interval 0.73 to 1.08. The upper end of that interval is the gene's LOEUF score, 1.08, which puts it in group 4 of 6, group 1 being the genes least tolerant of losing a copy. Missense variants: 909 observed, 943.39 expected, observed/expected ratio (o/e) 0.96, 90% interval 0.91 to 1.02. Synonymous variants: 353 observed, 377.65 expected, observed/expected ratio (o/e) 0.93, 90% interval 0.86 to 1.02.
Homologues: Orthologues: chimpanzee TGM7 (99% identical), macaque TGM7 (95% identical), dog TGM7 (83% identical), pig TGM7 (81% identical), guinea pig TGM7 (81% identical), rabbit TGM7 (80% identical), rat Tgm7 (78% identical), mouse Tgm7 (78% identical), zebrafish tgm5l (33% identical), zebrafish tgm8 (18% identical). Paralogues in human: TGM5 (50% identical), TGM6 (44% identical), TGM2 (40% identical), TGM3 (39% identical), TGM1 (36% identical), TGM4 (33% identical), EPB42 (31% identical), F13A1 (30% identical).
Diseases named in the same sentence as TGM7 in open-access papers:
TGM7 is named in the same sentence as 7 diseases in open-access papers, as found by Europe PMC text mining. Sharing a sentence is not in itself a finding about the gene and the disease. The quoted sentences say what the papers report.
gastric cancer (1 paper, 2020). A primary or metastatic malignant neoplasm involving the stomach. "In contrast, other transglutaminases including TGM1, TGM4, TGM5, TGM6, and TGM7 exhibited a significant decrease in gene expression in the gastric cancer tissue samples." (PMID 32467608, 2020).
type 2 diabetes (1 paper, 2017). "It is important to note that TGM2, TGM3, and TGM7 nsSNVs do not seem to be associated with any pathological phenotype except perhaps TGM2 heterozygous mutations associated with early-onset type 2 diabetes, an observation which has not been confirmed in animal experiments and large clinical cohorts." (PMID 28248968, 2017).
cancer (2 papers, 2017 to 2025). A tumor composed of atypical neoplastic, often pleomorphic cells that invade other tissues. "Neither UBAP1 nor TGM7 has a function that, based on known functionally relevant cancer-specific fusions (typically kinases, transcription factors, chromatin modifiers), is readily connected to tumorigenesis, therefore, it is difficult to speculate what role this fusion might serve." (PMID 28423358, 2017).
tumor (2 papers, 2022 to 2025). "Increased IL6 and TNFα expression in this study suggests that TGM7 silencing disrupts inflammatory regulation, creating a tumor-supportive microenvironment." (PMID 41425727, 2025). "In addition, TGM4, TGM6, and TGM7 genes were the lowest expressed and did not exhibit statistically significant differences in the level of expression between tumor and healthy tissues." (PMID 35725560, 2022).
TGM7 also shares sentences with these, for which no sentence is quoted: asthma (1 paper); colorectal adenoma (1); Germ Cell Tumors (1).